PYGB (glycogen phosphorylase B)
Diseases named in the same sentence as PYGB in open-access papers (continued):
Sharing a sentence is not in itself a finding about the gene and the disease.
McArdle disease (4 papers, 2015 to 2024). "Among the genes related to glycogen catabolism, PYGB, PYGL, and PYGM, only PYGM is expressed in muscle, which will lead to McArdle disease when it carries biallelic mutations." (PMID 38334681, 2024). "In genes related to glycogen catabolism, PYGB, PYGL, and PYGM, only PYGM is expressed in the muscle, and when carrying biallelic mutations it causes McArdle disease (glycogen storage disease type V)." (PMID 37185710, 2023). "Therefore, it was concluded that VPA enhanced the expression of PYGB in vitro and is expected to become a candidate for the treatment of McArdle disease." (PMID 38334681, 2024). "Theoretically, any pharmacological treatment that upregulates the PYGB expression in the skeletal muscle could be a potential therapeutic approach for patients with McArdle disease." (PMID 38334681, 2024). "Sodium valproate treatment in an ovine model of McArdle disease showed an increase in the expression of a PYGB, and primary cultures of myocytes isolated from McArdle knock-in mice showed that sodium valproate increased PYGB expression and reduced the accumulation of intracellular glycogen." (PMID 31775340, 2019). "Furthermore, VPA can enhance PYGB expression in vitro and could be a candidate for the treatment of McArdle disease." (PMID 25762569, 2015). "The potential demethylation treatment of CpG islands of the PYGB promoter could allow the activation and transcription of the PYGB gene in skeletal muscle from individuals with McArdle disease as an approach to compensate for the lack of GP-MM." (PMID 25762569, 2015).
colorectal cancer (3 papers, 2020 to 2024). A primary or metastatic malignant neoplasm that affects the colon or rectum. "PYGB has also been investigated as a diagnosis biomarker in human colorectal cancer." (PMID 38334681, 2024). "This indicated that PYGB could be used as a biomarker for the diagnosis of colorectal cancer." (PMID 38334681, 2024). "This suggests that PYGB-positive foci might be a candidate for early preneoplastic lesions, and it is expected to contribute to in-depth studies on the pathogenesis of “de novo” colorectal cancer." (PMID 38334681, 2024). "PYGB is expressed in colonic adenomas with a high grade of dysplasia, and the tumor and is frequently expressed in the transitional mucosa of colorectal cancer without an adenoma component." (PMID 38334681, 2024).
liver cancer (3 papers, 2023 to 2025). An epithelial or non-epithelial malignant neoplasm that arises from the liver. "Our finding aligned with prior research that has established comparable expression patterns of PYGB in ovarian and liver cancers." (PMID 40458414, 2025). "PYGB has been reported to be involved in the progression of gastric and liver cancers." (PMID 36936916, 2023).
myocardial infarction (3 papers, 2022 to 2024). Gross necrosis of the myocardium, as a result of interruption of the blood supply to the area, as in coronary thrombosis. "Recently, a meta-analysis of PYGB showed that it had moderate diagnostic accuracy for myocardial infarction (MI) and was superior to CK-MB and myoglobin." (PMID 38334681, 2024). "After that, their team published a detailed summary about PYGB in myocardial infarction, concluding that PYGB cannot be recommended as a diagnostic marker of AMI, neither as an independent indicator nor as an addition to troponin, which needs further investigation." (PMID 38334681, 2024). "The clinical application of PYGB is not only limited to traditional myocardial infarction." (PMID 38334681, 2024). "The involvement of genes such as AGPS, MYO9B, PYGB, TOM1, UBA52, and UBB in myocardial infarction is first reported in this study." (PMID 39872885, 2024).
pancreatic cancer (3 papers, 2016 to 2024). "It is also suggested that the expression of PYGB can promote the decomposition and utilization of glycogen by pancreatic cancer cells, improving the viability of pancreatic cancer cells in a glucose-deficient environment." (PMID 38334681, 2024). "They cultured the 2-DG (2-deoxy-D-glucose)-resistant pancreatic cancer cell line in a glucose-deprived environment for 72 h, and the results showed that the protein and mRNA levels of PYGB were reduced and the cell mortality was increased significantly compared with the primary cells." (PMID 38334681, 2024). "Similarly, another study found that human pancreatic cancer cell lines with low levels of glycogen phosphorylase B (PYGB) are more sensitive to glucose deprivation conditions, suggesting that PYGB could be a therapeutic target in those cancers with limited glucose levels." (PMID 26882899, 2016).
adenoma (2 papers, 2020 to 2024). A neoplasm arising from the epithelium. "A statistical analysis showed an excellent positive correlation between the expression of PYGB during the adenoma–carcinoma sequence (ACS) and increased dysplasia, whereas no PYGB expression was seen in the normal human large intestine away from the cancer foci." (PMID 38334681, 2024). "More importantly, PYGB overexpression was found during the conversion process from adenoma cells into carcinoma cells, which indicates that PYGB may be served as a prognostic biomarker for cancer from precancerous lesions." (PMID 33324633, 2020).
depression (2 papers, 2021 to 2024). "The glycogen level markedly increased in PYGB knockdown mice, and PYGB knockdown in the mPFC was found to increase susceptibility to depression-like behaviors." (PMID 35140588, 2021). "Behavioral tests on astrocyte-specific PYGB overexpression mice showed that augmenting astrocytic PYGB reduces susceptibility to depression when compared with stress-susceptible mice." (PMID 35140588, 2021). "In contrast, PYGB overexpression reduced the susceptibility to depression." (PMID 38334681, 2024). "Furthermore, PYGB overexpression in the mPFC decreases susceptibility to depression, at least partially by rescuing glycogen phosphorylase activity to maintain glycogen metabolism homeostasis during stress." (PMID 35140588, 2021). "On the contrary, augmenting astrocytic PYGB reduces susceptibility to depression." (PMID 35140588, 2021). "PYGB contributes to stress-induced depression-like behaviors and is a promising therapeutic target for the treatment of depression." (PMID 38334681, 2024). "Our findings provide evidence that PYGB plays a substantial role in glycogen accumulation, while identifying a new target for the development of innovative antidepressants to treat major depressive disorder." (PMID 35140588, 2021). "Specifically, PYGB was found to contribute to stress-induced depression-like behaviors, thus highlighting PYGB as a potential novel therapeutic target for the treatment of depression." (PMID 35140588, 2021). "Conversely, PYGB genetic down-regulation in the mPFC was sufficient to induce glycogen accumulation and depression-like behaviors." (PMID 35140588, 2021). "The study investigated whether astrocyte PYGB was involved in glycogen accumulation in depression by combining behavioral and genetic methods." (PMID 38334681, 2024). "To determine whether the stress-induced PYGB decrease in the mPFC is responsible for depression-like behaviors, we knocked down PYGB expression in astrocytes in the mPFC." (PMID 35140588, 2021). "In addition, we combined behavioral and genetic approaches to investigate whether astrocytic PYGB is involved in glycogen accumulation in depression." (PMID 35140588, 2021).
glycogen storage disease (2 papers, 2024). "PYGB is an enzyme that plays a key role in glycogen metabolism and dysregulation of PYGB can lead to glycogen storage diseases." (PMID 38610911, 2024). "Notably, 2/8 proteins that regulate the lysosomal storage disorder glycogen storage disease were highlighted in the EL network of AF and 2 more (PYGB and AGL) were significantly upregulated in TL." (PMID 38827406, 2024).
osteosarcoma (2 papers, 2020 to 2024). A usually aggressive malignant bone-forming mesenchymal neoplasm, predominantly affecting adolescents and young adults. "Studies have shown that PYGB has a higher expression level in osteosarcoma tissues, especially in the human osteosarcoma cell lines MG63 and HOS, compared to bone cysts." (PMID 38334681, 2024). "Therefore, it can be said that PYGB is a potential marker for the early clinical diagnosis and treatment of osteosarcoma, providing a new method for its treatment." (PMID 38334681, 2024).
Alzheimer disease (1 paper, 2024). A progressive, neurodegenerative disease characterized by loss of function and death of nerve cells in several areas of the brain leading to loss of cognitive function such as memory and language. "In a study to identify Alzheimer’s disease autoantibodies and their target biomarkers via phage microarray, researchers found that four receptors, including PYGB, could significantly distinguish AD from controls." (PMID 38334681, 2024).
brain injury (1 paper, 2023). Acute and chronic (see also brain INJURIES, CHRONIC) injuries to the brain, including the cerebral hemispheres, CEREBELLUM, and brain STEM. "The IC50 of PYGB inhibition was 90.27 nM, and it showed a better protective effect against ischemic brain injury." (PMID 37836837, 2023). "In addition, the PYGB inhibitor has been recognized as a kind of prospective drug for treating ischemic brain injury, and as a potential novel anti-ischemic stroke drug has a favorable prospect for research and development." (PMID 37836837, 2023).
cerebral ischemia (1 paper, 2024). Restriction of arterial blood supply to the brain associated with insufficient oxygenation to support the metabolic requirements of the tissue. "In recent years, Zhang’s group revealed a novel PYGB inhibitor involved in glucose metabolism, which has better inhibitory activity against PYGB and a potential therapeutic effect on brain ischemia." (PMID 38334681, 2024). "And the PYGB levels continue to rise for at least 48 h, allowing clinicians to establish a diagnosis of cerebral ischemia in patients with recent neurological symptoms." (PMID 38334681, 2024).
Cirrhosis (1 paper, 2024). A chronic disorder of the liver in which liver tissue becomes scarred and is partially replaced by regenerative nodules and fibrotic tissue resulting in loss of liver function. "Of the 36 cirrhosis variants, we identified protein-altering variants in LD (r2 > 0.8) with the lead variant at 16 loci, including 3 splice variants in HSD17B13 (rs72613567, c.812+2dupT), MAMSTR (rs11666792, c.219+3G>A) and PYGB (rs2261790, c.1518+6T>C)." (PMID 38632349, 2024).
gastrointestinal carcinoma (1 paper, 2020). "In cancers, PYGB attracts observation for its nuclear localization in some gastrointestinal carcinoma." (PMID 33324633, 2020).
ischemic disease (1 paper, 2023). Lack of blood supply to an area of the body, resulting in impairment of tissue oxygenation. "In this study, we validated whether PYGB could be used as the therapeutic target for hypoxic-ischemic diseases and investigated whether compound 1 exerts a protective effect against astrocyte hypoxia/reoxygenation (H/R) injury by targeting PYGB." (PMID 36838691, 2023).
lung adenocarcinoma (1 paper, 2025). A carcinoma that arises from the lung and is characterized by the presence of malignant glandular epithelial cells. "First, we constructed siRNA targeting PYGB in human lung squamous carcinoma (NCI-H226) cell line and human lung adenocarcinoma cell line." (PMID 40458414, 2025). "To explore the role of PYGB in LC proliferation, migration, and invasion in vitro, we constructed siRNA targeting PYGB in Human lung squamous carcinoma cells (NCI-H226) line and Human lung adenocarcinoma cells line." (PMID 40458414, 2025).
ovarian tumor (1 paper, 2021). "The expression levels of ANGPTL4, PYGB and IRS2 were upregulated and those of ISG20 and SEH1L were downregulated in ovarian tumor tissues compared with normal tissues." (PMID 34229669, 2021). "Consistent with other studies, we observed that ANGPTL4, PYGB and IRS2 were highly expressed in ovarian tumor tissues and patients with high expression of ANGPTL4, PYGB or IRS2 had significantly lower OS rates than patients with low expression of these factors." (PMID 34229669, 2021).
preeclampsia (1 paper, 2024). Preeclampsia is a hypertensive disorder of pregnancy that is characterized by new-onset hypertension with proteinuria presenting after 20 weeks of gestation, and depending on mild or severe forms may initially present with severe headache, visual disturbances, and hyperreflexia. "Studies have suggested that there is currently insufficient evidence to support PYGB as a useful diagnostic or prognostic indicator in preeclampsia or SPE." (PMID 38334681, 2024). "That is to say, PYGB can be used as a biomarker for early pregnancy and in the prediction of premature and full-term preeclampsia and SGA onset." (PMID 38334681, 2024). "A team from Ireland came to this conclusion in their research, showing that the PYGB concentrations had significant variations in normal pregnancy, preeclampsia, and SGA pregnancy." (PMID 38334681, 2024). "The PYGB levels were significantly elevated in patients with the early onset of eclampsia, but not in patients with preeclampsia at term." (PMID 38334681, 2024).
respiratory failure (1 paper, 2021). The significant impairment of gas exchange within the lungs resulting in hypoxia, hypercarbia, or both, to the extent that organ tissue perfusion is severely compromised. "PYGB (ZTWAS = −6.98, PIP = 0.999, lung SNP weights) encodes a protein involved in glycogenolysis and can be putatively inhibited by the new exploratory treatment for respiratory failure, sivelestat." (PMID 33720009, 2021).
Stroke (1 paper, 2024). Sudden impairment of blood flow to a part of the brain due to occlusion or rupture of an artery to the brain. "Insulin can also activate the PKA-PhK-GP pathway, and the neuroprotective effect of insulin can be weakened by PYGB knockdown, which may be the reason for the insulin-mediated recovery in the acute and subacute phases after stroke." (PMID 38334681, 2024). "The PYGB levels were above the upper reference limit within the first 4.5 h of stroke onset." (PMID 38334681, 2024). "Therefore, PYGB can be used as a screening indicator for the early diagnosis of suspected stroke." (PMID 38334681, 2024). "Although PYGB has been shown to be a sensitive marker for diagnosing AIS, it can be used as a screening marker for the early diagnosis of suspected stroke." (PMID 38334681, 2024).
unstable angina (1 paper, 2024). "Elevated PYGB levels were also found (at 3 h) in 93.9% of patients who received the final diagnosis of unstable angina." (PMID 38334681, 2024).
cancer (20 papers, 2016 to 2025). A tumor composed of atypical neoplastic, often pleomorphic cells that invade other tissues. "There is evidence that PYGB is associated with the progression of varied human malignant tumors, regulating the proliferation, invasion, and apoptosis of cancer cells, and other biological characteristics." (PMID 38334681, 2024). "Moreover, the dysregulation of PYGB has been implicated in various pathologies, including cancer, where its activity can influence tumor growth and progression." (PMID 40458414, 2025). "Additionally, 40/64 genes were linked to two or more cancers, with glycogen phosphorylase B (PYGB) and lamin B1 (LMNB1) having the most associations with seven cancer types." (PMID 39119785, 2024). "In addition, we found that high expression of the PYGB gene was associated with the G2/M cell cycle checkpoint, cancer cell proliferation, DNA damage repair, and MYC gene expression." (PMID 38483604, 2024). "Moreover, PYGB was associated with the poor prognosis of cancer and can promote the proliferation and invasion of cancer cells by activating Wnt/β-catenin signaling." (PMID 33292266, 2020). "CAMK2A displayed broad positive correlations, with distinct clusters of strong associations in several cancers, whereas CHMP4C and PYGB exhibited heterogeneous profiles characterized by both positive and negative associations." (PMID 41180485, 2025). "Evidence suggests that increased glycogen metabolism via PYGB is crucial for maintaining cellular energy levels and preventing premature senescence in cancer cells." (PMID 40458414, 2025). "We systematically analyzed PYGB in LC using data from the Cancer Genome Atlas (TCGA) and the Gene Expression Omnibus (GEO) Cancer database, employing R and various online analytical tools." (PMID 40458414, 2025). "Recent studies have highlighted the role of PYGB in metabolic reprogramming within cancer cells, particularly under hypoxic conditions commonly found in tumor microenvironments." (PMID 40458414, 2025). "To determine the potential role of PYGB in human cancers, we first examined the expression levels of the PYGB gene in pan-cancer using the TIMER 2.0 database." (PMID 38483604, 2024). "Pan-cancer analysis showed that PYGB was highly expressed in most of the tumors but had the highest correlation with PC." (PMID 38483604, 2024). "Here, we explore the role of PYGB in cancer and propose that PYGB is a promising target for the development of new medications." (PMID 38334681, 2024). "According to different enrichment analysis methodologies, we found that PYGB promotes cancer by acting as a link between various oncogenic pathways." (PMID 38483604, 2024). "Although breast cells have increased glycogen storage under hypoxic conditions, PYGB-promoted glycogen utilization affects the migration and invasion of cancer cells." (PMID 38334681, 2024). "Detected via the TCGA database and an IHC analysis of patient specimens, compared to normal tissues, the mRNA and protein levels of PYGB in cancer tissues were significantly increased." (PMID 38334681, 2024). "The overexpression of PYGB has been observed in various cancer types, and it has been reported that PYGB can regulate the malignant phenotypes of cancer cells." (PMID 38334681, 2024). "All these findings suggest that PYG enzymes, and in particular PYGB, play an important role in cancer biology." (PMID 35897773, 2022). "PYGB is a glycogen phosphorylase that is predominantly expressed in the brain but also expressed in several types of cancer." (PMID 34243818, 2021). "As we predicted, the expression of PYGB is enhanced in the cancer tissues of 60 women with OC compared with normal ovarian tissues." (PMID 32880385, 2020). "PYGB expression was dysregulated in a series of cancer tissues compared with the corresponding normal tissue." (PMID 33324633, 2020). "PYGB is an enzyme that metabolizes glycogen and can influence the growth and apoptosis of the cancer cell by regulating the NF‐κB/Nrf2 signaling pathway." (PMID 33292266, 2020).